CGAS (cyclic GMP-AMP synthase)
Diseases named in the same sentence as CGAS in open-access papers (continued):
Sharing a sentence is not in itself a finding about the gene and the disease.
liver cancer (14 papers, 2020 to 2026). An epithelial or non-epithelial malignant neoplasm that arises from the liver. "Another important finding in the present study is that the expression of cGAS-STING pathway members is associated with various immune cell infiltration levels in liver cancer." (PMID 33006365, 2020). "In the context of liver cancer, radiotherapy activates the cGAS-STING pathway within tumor cells, leading to the secretion of IFN-I and the enhancement of CD8+ T cell activity." (PMID 41522604, 2026). "Our prior research indicates a significant association between cGAS‐STING pathway activation and NAFLD, liver lipid drop disturbance, as well as liver cancer immunotherapy." (PMID 39877286, 2025). "We next investigate how cGAMP produced by cGAS in liver cancer cells is transported to endothelial cells." (PMID 38177099, 2024). "In Human Protein Atlas (HPA), cGAS was positive expressed in liver cancer cells from most patients, but positive STING expression in cancer cells was only detected in one of 12 patients." (PMID 38177099, 2024). "Excitingly, VC treatment dramatically induced cGAS expression at both the transcript and protein levels in liver cancer cells in vitro." (PMID 38177099, 2024). "Together, these results indicate that IL-2-activated STAT5A recruits TET2 binding to the cGAS locus to promote cGAS demethylation and transcription, leading to cGAS upregulation in liver cancer." (PMID 38177099, 2024). "To further verify this phenomenon in human liver cancer, we established cGAS stably expressed human liver cancer cells (Huh7), which lack intrinsic cGAS and STING expressions, and forced cGAS expression did not alter Huh7 cells proliferation in culture." (PMID 38177099, 2024). "Next, we verified the activation of endothelial STING by liver cancer cell cGAS through in vitro experiments." (PMID 38177099, 2024). "Expectedly, we further demonstrate that as a TETs enzyme activator, VC treatment increases cGAS expression via TET2-dependent demethylation in liver cancer cells." (PMID 38177099, 2024). "Gene set enrichment analysis (GSEA) (Panther pathway analysis) revealed that tumor cGAS was highly interrelated with both T cell activation and angiogenesis in liver cancer from TCGA, indicating the regulatory role of tumor cGAS in vasculature remodeling." (PMID 38177099, 2024). "We further verified the regulation of tumor cGAS by TET2 and STAT5A signaling in human liver cancer samples and found that high tumor TET2 and p-STAT5A expressions were associated with high tumor cGAS expression." (PMID 38177099, 2024). "When Yap1 was knocked out in liver cancer tissues, the expressions of cGAS and STING decreased." (PMID 40918140, 2025). "To further investigate whether TET2 regulates cGAS expression, we overexpressed Tet1, Tet2, and Tet3 in liver cancer cells, respectively." (PMID 38177099, 2024). "Together, these findings suggest that TET2 is a major mediator of cGAS expression in liver cancer." (PMID 38177099, 2024). "Through bioinformatics analysis, we found that YAP1 was positively related to cGAS and STING in liver cancer (cor/R>0 and P<0.05)." (PMID 40918140, 2025). "Our findings also confirmed that YAP1 was positively related to cGAS, STING, and GSDMD in liver cancer tissues." (PMID 40918140, 2025). "The combined action of inhibiting the cGAS/STING pathway and YAP1 results in a better therapeutic effect on liver cancer." (PMID 40918140, 2025). "A recent study found that cyclic GMP-AMP synthase (cGAS), anchored to the outer mitochondrial membrane, binds to dynamic-related protein 1 (DRP1) to facilitate its oligomerization, and protects liver cancer cells from ferroptosis." (PMID 38347570, 2024). "Here the authors show that TET2 upregulates tumor cGAS to activate STING in endothelial cells, inducing tumor vascular normalization and enhancing efficacy of anti-PD-L1 alone or combined with IL-2 in liver cancer preclinical models." (PMID 38177099, 2024).
liver cancer (continued). "Together, these results confirm the vital role of tumor cGAS and host STING activation in VC-mediated vascular normalizing effects and the combinational efficiency of VC and anti-PD-L1 therapy in liver cancer." (PMID 38177099, 2024). "Together, we identify the interdependence between tumor cGAS and host STING in the regulation of vasculature remodeling and anti-tumor immunity in liver cancer." (PMID 38177099, 2024). "We further assessed the correlation between tumor cGAS and endothelial STING activation in human liver cancer." (PMID 38177099, 2024). "After correlation adjustment by purity, we found that the expression levels of cGAS-STING pathway members were significantly related with most immune marker sets of different immune cells and various functional T cells in liver cancer." (PMID 33006365, 2020). "We next analyzed the correlation between the mRNA expression of cGAS-STING pathway members and the pathological stage of patients with liver cancer according to UALCAN." (PMID 33006365, 2020). "DDP increased the expression of cGAS and STING in liver cancer tissue." (PMID 40918140, 2025). "Hyperbaric oxygen promotes cGAS‐STING activation, aiding liver cancer immunotherapy." (PMID 39877286, 2025). "Taken together, these results indicated that the synergistic effect of ROD hydrogel promoted the recruitment and maturation of imDCs, activated the cGAS/STING/IFN-I pathway, enhanced the antitumor immunity, and thus improved the treatment efficacy against residual liver cancer after iRFA therapy." (PMID 37919724, 2023). "The present work identifies TET2 methylcytosine dioxygenase as a responsible enzyme for cGAS demethylation and reveal that activated STAT5A recruits TET2 binding to the cGAS locus to promote cGAS demethylation and transcription, resulting in cGAS upregulation in liver cancer cells." (PMID 38177099, 2024). "The cGAS-STING pathway members exhibited significant correlations with immune infiltrating cells in HCC, and may play an important role in immune escape in the liver cancer microenvironment." (PMID 33006365, 2020). "With Yap1 expression knocked out, DDP no longer increased the expressions of cGAS and STING in liver cancer." (PMID 40918140, 2025). "In human liver cancer cell lines HepG2 and PLC/PRF/5 that express little or no cGAS proteins, stably reconstitution of cGAS via lentiviral infection led to marked suppression of ALDH2 activity, as indicated by reduced NAD+ to NADH conversion." (PMID 41042077, 2025).
prostate carcinoma (14 papers, 2019 to 2026). A carcinoma that arises from epithelial cells of the prostate gland. "Under certain conditions, Cutibacterium acnes is known to cause deep tissue infections and promote prostate cancer tumorigenesis through interferon-1 signalling and the cGAS-STING pathway." (PMID 38027096, 2023). "By trapping PARP on damaged chromatin and augmenting unresolved DNA lesions, PARP inhibitors promote the generation of micronuclei and cytoplasmic DNA in prostate cancer and instigate activation of the cGAS–STING pathway." (PMID 41488638, 2025). "In a prostate cancer model, PARPi combined with PI3Ki can induce tumor regression by activating the cGAS/STING pathway within the TAM." (PMID 41488638, 2025). "Mechanistically, docetaxel treatment upregulates the cGAS/STING pathway in prostate cancer, subsequently activated IFN signaling, resulting in lymphocytes infiltration." (PMID 35836810, 2022). "We hypothesize that TREX1 functions as an “innate immune checkpoint” in prostate cancer by attenuating cGAS-STING signaling, thereby facilitating immune evasion and disease progression; nonetheless, this proposition warrants further experimental validation." (PMID 41346575, 2025). "Herein, we evaluated the influence on immune cell infiltration and T‐cell effector function in prostate cancer‐bearing mice to study the immune reaction evoked by CIR and explored the mechanisms underlying CIR‐induced antitumor efficacy, involved in cGAS–STING signaling pathway." (PMID 38379323, 2024). "Moreover, we found that docetaxel activated the cGAS/STING pathway in prostate cancer, subsequently induced IFN signaling, resulting in lymphocytes infiltration." (PMID 35836810, 2022). "Similarly, our findings suggest that PCBP2 may suppress the cGAS-STING pathway in prostate cancer, potentially leading to PD-L1-mediated immune evasion." (PMID 40051782, 2025). "Additionally, by mining the prostate cancer dataset from TCGA, we observed a direct correlation between high cGAS expression and better survival, suggesting that cGAS could play a protective role in prostate cancer patient prognosis." (PMID 35836810, 2022). "Reduced activity of the cGAS-STING pathway, together with decreased level of CXCL9, CXCL10, CXCL11, IFNβ, and IL-10 were observed in castration-resistant prostate cancer." (PMID 40940894, 2025). "PARPi activates cGAS-STING signaling and recruits immune cells within the prostate cancer bone metastatic niche." (PMID 41488638, 2025). "While the cGAS-STING pathway has been well studied in tumor immunity, our findings provide novel insights into how PCBP2 specifically suppresses this pathway in prostate cancer, leading to immune evasion." (PMID 40051782, 2025). "Altogether, these data indicated docetaxel-based chemohormonal therapy can trigger DNA release into the cytosol, thereby activating the cGAS/STING pathway, which leads to IFN-stimulated genes response in prostate cancer cells." (PMID 35836810, 2022). "In prostate cancer cells, MUS81 is responsible for cytoplasmic single‐stranded DNA (ssDNA) that is detected by the cGAS‐STING pathway, and is responsible for interferon induction that can recruit macrophages to control tumour growth." (PMID 31044505, 2019). "The excellent antitumor activity of CIR in immunocompetent prostate cancer‐bearing C57BL/6 mice may be attributed to stronger induction of antitumor immune response and higher activation of cGAS–STING pathway." (PMID 38379323, 2024). "Taken together, we believed that CIR could activate cGAS–STING signaling pathway and be responsible for the inhibition of tumor growth in prostate cancer‐bearing mice." (PMID 38379323, 2024). "All these results strengthen our hypothesis that the cGAS/STING pathway serves as a functional effector, at least partially, mediating the growth inhibition induced by combined therapy in prostate cancer." (PMID 35836810, 2022).
prostate carcinoma (continued). "Here, we show that the cGAS-STING pathway was unresponsive to STING agonists and failed to induce type I interferon (IFN) expression in many tested human tumor cells including DU145 prostate cancer cells." (PMID 33790360, 2021). "Notably, cGAS–STING activation is time restricted and potentially self-limiting in prostate cancer." (PMID 41488638, 2025). "Although MN were not increased in prostate cancer patients, it is important to ponder whether NPB, like MN, may also be a source of DNA leaking into the cytoplasm and triggering the pro-inflammatory cGAS-STING pathway." (PMID 37444460, 2023).
asthma (12 papers, 2021 to 2025). "In our study, we found that GSDMB, the asthma risk gene located in the 17q21, promotes the activation of mtDNA-induced cGAS-STING pathway via facilitating the translocation of STING into Golgi and subsequent interaction with TBK1." (PMID 38737375, 2024). "Additionally, HSP90α plays a role in the cGAS-STING-ER stress pathway associated with HDM-induced asthma, resulting in the pyroptosis of airway epithelial cells." (PMID 40826442, 2025). "Polyvinyl chloride (PVC) nanoplastics (NPs) are shown to aggravate allergic airway inflammation in asthma by triggering R‐loop accumulation and activating the cGAS‐STING pathway in macrophages." (PMID 40919700, 2025). "DNA release into the cytosol and cGAS activation seem to play a role in asthma and allergic inflammation." (PMID 40264103, 2025). "Cytosolic DNA and cGAS were found co-localized in human bronchial cells treated with IL-33, an inflammatory cytokine involved in the asthma attack." (PMID 40264103, 2025). "While the genetic analyses have identified the association between GSDMB and interferon response, the molecular mechanisms and ensuing biological effects of GSDMB in mtDNA-induced cGAS-STING pathway in the context of asthma remain largely undefined." (PMID 38737375, 2024). "Targeting the cGAS-STING pathway may provide a feasible therapeutic approach for asthma." (PMID 41226461, 2025). "Consequently, drugs targeting the inhibition of the cGAS-STING pathway May become new therapeutic agents for treating airway inflammation in asthma." (PMID 39540037, 2024). "Therefore, activation of the cGAS–STING signaling pathway may be responsible for the immune response observed during asthma attacks." (PMID 38525112, 2024). "In this study, we identified R‐loop accumulation as a key cellular event in PVC NPs‐induced inflammation in macrophages, demonstrating how R‐loop accumulation activates the cGAS‐STING pathway, thus offering new insights into the pathogenesis of asthma." (PMID 40919700, 2025). "Therefore, the cGAS–STING pathway probably contributes to the immune response at the onset of asthma; However, whether cGAS itself is involved in this immune response, or whether cGAS activates the immune response through the cGAS–STING pathway, further studies are necessary to confirm." (PMID 34906241, 2021). "Targeting the cGAS‐STING pathway, a central mediator of innate immune inflammation, may represent a novel strategy for mitigating pollutant‐aggravated asthma." (PMID 40919700, 2025). "In this context, the cGAS–STING signaling pathway has been widely studied because of its importance in the occurrence of lung inflammatory diseases, such as chronic obstructive pulmonary disease (COPD), pulmonary fibrosis (PF), and asthma." (PMID 38525112, 2024).
chronic kidney disease (12 papers, 2021 to 2025). Impairment of the renal function secondary to chronic kidney damage persisting for three or more months. "Researchers initially observed that chronic kidney disease recruits activation of the cGAS–STING pathway, and that this activation is associated with abnormalities in mitochondrial metabolism." (PMID 34906241, 2021). "A more detailed exploration of the involvement of the cGAS/STING pathway in the progression to LN end-stage renal disease (LN-ESRD) using cultured human podocytes was recently reported." (PMID 38473743, 2024). "Chronic kidney disease (CKD)-induced oxidative stress culminates in mitochondrial damage to trigger cGAS-STING activation and IFN production in vascular smooth muscle cells (VSMCs), increasing atherosclerotic plaque vulnerability." (PMID 37354378, 2023). "In a 2019 study, researchers also affirmed the contribution of the cGAS–STING pathway to the development of chronic kidney disease." (PMID 34906241, 2021). "Another study on the development of LN-related end-stage renal disease in African-Americans also confirmed the essential role of the cGAS–STING pathway in renal disease." (PMID 34906241, 2021). "Notably, the cGAS–STING pathway has been implicated in metabolic syndrome and chronic kidney disease, suggesting broader relevance for our findings." (PMID 41300433, 2025). "Even in the context of chronic kidney disease (CKD), the cGAS-STING pathway plays a significant role in the development of atherosclerotic (AS) plaques." (PMID 39664570, 2024). "Recently, molecules typically associated with an antiviral immune response, cyclic GMP-AMP synthase (cGAS) and stimulator of interferon genes (STING), have been linked to the development of chronic kidney disease (CKD) in the absence of infection." (PMID 38473743, 2024).
ischemia (12 papers, 2020 to 2025). A hypoperfusion of the BLOOD through an organ or tissue caused by a PATHOLOGIC CONSTRICTION or obstruction of its BLOOD VESSELS, or an absence of BLOOD CIRCULATION. "In the liver, malfunctioning of kupffer cells or monocytes-derived macrophages and hepatocytes is linked with mtDNA release and cGAS activity causes various liver diseases including hepatic ischemia-reperfusion injury, and hepatic cancer." (PMID 36139387, 2022). "Targeted inhibition of the overactivated cGAS-STING signaling pathway after acute cerebral infarction can alleviate ischemia-reperfusion injury and reduce brain tissue damage." (PMID 39741707, 2024). "Cell death occurring from post-drug-induced nephrotoxicity, diabetic nephropathy, and ischemia-induced renal injury also activated cGAS-STING activation in the renal tubules." (PMID 36139387, 2022). "The cGAS-STING signaling activates in response to the cytosolic dsDNA, and HDAC3 promotes cGAS transcriptional expression in microglia during ischemia/reperfusion-induced brain injury." (PMID 33643304, 2020). "Moreover, unlike pathways such as TLRs that rely on extracellular or endosomal signals, cGAS-STING operates directly within the cytoplasm, making it more responsive to intracellular disruptions associated with ischemia." (PMID 39741707, 2024). "Importantly, an original study targeting the cGAS–STING axis with intranasal delivery of the RU.521 demonstrated its neuroprotective roles in the brains of an experimental neonatal hypoxia–ischemia rat model." (PMID 35689216, 2022). "During diabetic myocardial ischaemia–reperfusion (MI/R), it remains unclear whether reduced mitochondrial fusion exacerbates myocardial injury by generating free damaged mitochondrial DNA (mitoDNA) and activating the cGAS-STING pathway." (PMID 37537600, 2023). "Hence, cGAS-STING signaling also plays a crucial role in ischemia/reperfusion-induced brain injury." (PMID 33643304, 2020). "Animal model studies have shown that inhibiting the cGAS-STING pathway can reduce the inflammatory response and tissue damage in ischemia-reperfusion injury of acute cerebral infarction, suggesting the potential of inhibitors targeting this pathway." (PMID 39741707, 2024). "So far, there have been no clinical studies related to the cGAS-STING pathway in acute cerebral infarction -related ischemia-reperfusion injury." (PMID 39741707, 2024).